IL6 (interleukin 6)
Diseases named in the same sentence as IL6 in open-access papers (continued):
Sharing a sentence is not in itself a finding about the gene and the disease.
steatosis (198 papers, 2008 to 2026). Increased lipid within the cytoplasm of cells. "Among various cytokines and chemokines, tumor necrosis factor-alpha (TNF-α) and interleukin-6 (IL-6) are recognized as crucial mediators associated with hepatic inflammation and steatosis." (PMID 40863135, 2025). "The resistance to steatosis was linked to an increase in inflammation-associated hepatic IL-6/STAT3 activation, which in turn caused the liver to downregulate lipogenic genes and upregulate genes linked to fatty acid oxidation." (PMID 38535313, 2024). "In a study on Caucasian NAFLD patients, the presence of the IL-6 rs1800795 C allele accompanied an escalated risk for severe steatosis, whereas it was associated with less IL-6 expression in the liver and lower progressive inflammation and fibrosis." (PMID 38504356, 2024). "The percent steatosis and liver lymphocyte infiltration were associated with BMI (r = 0.31, r = 0.29, p < 0.05) and with the level of plasma IL-6 (r = 0.39, r = 0.26, p < 0.05)." (PMID 33579000, 2021). "Feeding alcohol to MCP-1–deficient mice results in less steatosis, lower expression of pro-inflammatory cytokines (i.e., of TNFα, IL-1β, and IL-6), and lower levels of oxidative stress than in wild-type mice." (PMID 26695748, 2015). "Of note, under a normal diet, the steatosis and lobular inflammation scores were similar in WT and IL6-deficient mice." (PMID 19936233, 2009). "IL-6 also possesses pro-inflammatory properties, inducing the production of acute phase proteins, causing liver damage, and promoting liver aging, fibrosis, steatosis, and carcinogenesis." (PMID 41282626, 2025). "Upstream targets TNFα and JNK1/2 activate c-Jun and AP1 proteins, resulting in the production of downstream inflammatory factors like IL-6 and IL-1, which are closely associated with cell death in the steatosis liver observed in non-alcoholic fatty liver disease." (PMID 38429802, 2024). "The R70Q substitution is related to the increased expression of IL-6, which may cause IR, steatosis, and HCC and inhibit IFN signaling, which is associated with therapeutic failure." (PMID 36680226, 2023). "In the multidrug-resistant gene 2 knockout (Mdr2-/-) mice where 50% of the mice develop tumors after chronic injury, IL-6 signal deficiency led to more severe steatosis and inflammation presumably due to the inability of hepatocyte regeneration/increased hepatocyte apoptosis after injury." (PMID 36276076, 2022). "● IL-6 causes adipocyte lipolysis and muscle steatosis, dysmetabolism, and wasting." (PMID 36465353, 2022). "Like IL-6 and TNFα, IL-1 is commonly induced in steatotic livers when macrophage proliferation and infiltration are induced and is necessary for the whole spectrum of pathologies associated with steatosis, injury and cancer." (PMID 36276076, 2022). "From weeks 8 to 13, disease progressed in FFC-fed animals from simple steatosis with slight signs of inflammation to macrovesicular steatosis with an increase in the number of inflammatory foci also associated with elevated levels of proinflammatory cytokines like TNFα and IL6." (PMID 32235497, 2020). "However, the histological analysis of the liver sections of IL-6-deficient mice fed a HFD showed steatosis exacerbation after treatment with rIL-6." (PMID 26035386, 2015). "While the exact mechanism remains unclear, the heightened production of inflammatory cytokines such as C‐reactive protein, interleukin 6 and tumour necrosis factor‐alpha from hepatic adipose tissue associated with steatosis may play a significant role in this association." (PMID 40140729, 2025). "Notably, IL-6 deficiency negatively affected the expression or activation status of enzymes involved in the fatty acid β-oxidation process in liver, which contributed to the aggravation of steatosis." (PMID 26035386, 2015).
steatosis (continued). "Histological evaluation revealed a significant reduction in microvesicular steatosis and IL‐6 immunoreactivity scores exclusively in the synbiotic group, indicating alleviated hepatic lipid accumulation and inflammation." (PMID 40654532, 2025). "CD47 deficiency enhances NF-κB activation, elevates IL-1β, TNFα, IL-6, reduces IL-10, increases CCL2 and macrophage infiltration, leading to exacerbated steatosis, inflammation, and fibrosis." (PMID 40630093, 2025). "Our study further supplements the value of inflammatory markers, especially NLR and IL-6, in the early identification of the simple steatosis stage." (PMID 41377803, 2025). "In high-fat diet-induced fatty liver disease models, IL-6 or gp130 gene knockout resulted in significant improvement in liver inflammation and steatosis, as well as varying degrees of inhibition of tissue remodeling and fibrosis." (PMID 39995661, 2025). "Enhance the expression of ZO-1, Claudin-1 and Occludin, decrease the expression of LPS, TNF-α, IL-6 and IL-1β, enhance intestinal barrier, and reduce inflammatory response, hepatocyte steatosis and collagen fiber deposition." (PMID 39234554, 2024). "On the contrary, IL-6 also exerts the pro-inflammatory functions to induce liver aging, fibrosis, steatosis, and carcinogenesis." (PMID 38890694, 2024). "In IL-10(−/−) animals, further deletions of IL-6 or hepatic STAT3 increased the inflammatory response in the liver but reversed steatosis and hepatocellular damage." (PMID 38535313, 2024). "In the current study, BC juice decreased the expression of IL-6 mRNA and restored glucose regulation, indicating an anti-inflammatory effect in the liver and a possible role in the prevention of steatosis and glucose intolerance induced by the HFF diet." (PMID 38590904, 2024). "It is shown that individuals with NASH had significantly higher levels of hepatic IL-6 expression than patients with simple steatosis or normal biopsies, indicating the existence of hepatic IL-6 expression in human NASH." (PMID 38535313, 2024). "Pro-inflammatory cytokines i.e., TNF-α, IL-6 and IL-1β participate in the progression of simple steatosis to NASH by influencing hepatocyte apoptosis and necrosis, neutrophil chemotaxis, stellate cell activation, and Mallory body production." (PMID 36769216, 2023). "The development of tumors is preceded by the increased expression of interleukin-6 (IL-6), early-onset glucose intolerance, progressive steatosis and liver dysplasia." (PMID 37370771, 2023). "IL-6 expression was significantly increased in the hepatic biopsy of patients with nonalcoholic steatohepatitis (NASH) than patients having simple steatosis or normal biopsies." (PMID 36604518, 2023). "Derived from macrophage p38α-deficient mice, the primary hepatocytes showed decreased steatosis and inflammatory damage through reduced secretion of pro-inflammatory cytokines (TNF-α, CXCL10, and IL-6), which regulate M1 macrophage polarization." (PMID 36984693, 2023). "Simulations of a clinical protocol of tocilizumab in BIOLOGXsym leveraging the mechanistic toxicity data from LAMPS (i.e., induction of steatosis and ROS) and blockade of IL-6 signaling reproduced clinically observed and modest ALT elevations." (PMID 37298645, 2023). "In contrast, chronic IL-6 administration has been reported to aggravate steatosis in diet-induced obese mice and in IL-6−/− mice fed HF diet." (PMID 35470093, 2022). "In this latter model, the TNF-α and interleukin-6 (IL-6) serum levels were significantly elevated, as well as the expression of mRNAs related to lipogenesis, oxidative stress, fibrosis and steatosis." (PMID 36555433, 2022). "SCAPΔL mice exhibited significantly increased liver tumor development accompanied by significant elevation of IL-6, despite a mild reduction in hepatic steatosis." (PMID 35380992, 2022).
steatosis (continued). "Afterwards, an in vivo study showed that inhaled PM2.5 pollutants induces steatosis and portal inflammation with increasing expression of inflammatory factors such as IL-6, TNF-α, NF-κB in the liver." (PMID 36011940, 2022). "Instead, serum IL-6 levels had significant correlations with liver fat content, and increased IL-6 reflected the severity of steatosis." (PMID 35663311, 2022). "Activation of classic IL-6 signaling in steatosis leads to increased proliferation of liver cells and the replication stress due to the accumulation of replication errors, contributing to the progression of pathogenesis and degeneration of hepatocytes." (PMID 33579000, 2021). "The N800 treatment induced high levels of serum CCL2 and IL-6, accompanied by the appearance of steatosis in both propacetamol-poisoned and normal mice." (PMID 33809388, 2021). "Our results suggest a feed-forward signaling loop between tumor-derived IL-6, skeletal muscle steatosis and production of sIL6R, and adipose tissue IL-6 production working in concert to exacerbate skeletal muscle wasting in PDAC." (PMID 33851955, 2021). "The IL-6 expressions were detected in liver sections of the N800 group with steatosis, mainly localized in hepatocytes." (PMID 33809388, 2021). "This carotenoid suppressed proinflammatory cytokines secretion (TNF-α and IL-6) reversing inflammation, steatosis, and fibrosis progression in NASH by repressed macrophage activation." (PMID 33628797, 2021). "In the univariate analyses, it was observed that increasing IL-6 and TNF-α levels were significantly associated with liver enzymes according to the three groups, with increasing levels of melatonin, and with steatosis and fibrosis." (PMID 34221262, 2021). "In this regard, active macrophages increase the secretion of inflammatory cytokines, such as TNF-α and IL-6, which can further aggravate hepatocyte steatosis." (PMID 32326594, 2020). "FFC-fed mice progressed from simple steatosis to early non-alcoholic steatohepatitis, along with significantly higher TNFα and IL-6 protein levels in the liver and impaired glucose tolerance." (PMID 32235497, 2020). "Thereafter, NAFL progressed to NASH in mice after 8-week PEWD feeding, characterized with advanced steatosis, inflammatory cell infiltration, and elevation of pro-inflammatory cytokines, including Il-6, Tnf-α, and Tgf-β in liver." (PMID 31949129, 2020). "Hepatic IL-6 expression is known to be elevated in the livers of patients with NASH as compared to patients with simple steatosis or normal liver biopsies." (PMID 30024933, 2018). "AST, ALT, γGT, CRP, TNF-α and IL-6 as well as the histological characteristics (steatosis and fibrosis of the patients) were significantly improved compared with the patients who received the placebo." (PMID 28820468, 2017). "IL-6 is markedly up-regulated in steatotic livers, indicating a possible link among steatosis, IL-6, and LBP." (PMID 28216979, 2017). "In that case, the aggravation of steatosis observed after treatment with IL-6 was accompanied by up-regulation of lipogenic enzymes." (PMID 27333268, 2016). "The expression of interleukin-6 (IL-6) is markedly increased in the liver cells of patients with simple steatosis (P < 0.005) or NASH (P < 0.010) compared to normal subjects." (PMID 27891128, 2016). "The results presented herein indicate that, the administration of exogenous IL-6 in WT mice worsened the steatosis." (PMID 27333268, 2016). "IL-6 administration in rodents has yielded contradictory results regarding its effects on steatosis progression." (PMID 27333268, 2016). "The status and expression of IL-6-signalling mediators and targets were investigated in relation to the steatosis and lipid content in blood and in liver." (PMID 27333268, 2016). "In a recent study we showed that the chronic replacement of IL-6 with physiological doses in IL-6-/- mice seriously aggravates the steatosis induced by a high-fat diet." (PMID 27333268, 2016).
steatosis (continued). "To further examine the effects of IL-6 in NAFLD we induced steatosis in WT mice with a HFD for 16 weeks." (PMID 27333268, 2016). "In IL-6−/− mice fed HFD, the hepatic expression of CPT1 and AMPK activity remained at basal levels, which likely promote a deficit in the fatty acid oxidation process, thereby contributing to the steatosis aggravation in IL-6−/− mice." (PMID 26035386, 2015). "Evidence from the present study indicates a direct role of IL-6 on the expression of hepatic lipogenesis enzymes and steatosis exacerbation during exposure to an obesogenic diet." (PMID 26035386, 2015). "Recent findings suggest that alcohol-induced oxidative stress stimulates the expression of IL-6, promoting senescence in hepatocytes, which, in turn, makes cells more resistant to steatosis and apoptosis." (PMID 26695748, 2015). "The liver sections from IL-6−/− mice fed a HFD revealed severe steatosis, exhibiting extensive fatty degeneration in hepatocytes containing pale foaming cytoplasm." (PMID 26035386, 2015). "IL-6 release from M2 macrophages induces senescence and blocks apoptosis and steatosis in hepatocytes in the early stage of alcohol-induced liver injury in mice." (PMID 26695748, 2015). "In this study, we further investigated the role of IL-6 on steatosis induced through a high-fat diet (HFD) in wild-type (WT) and IL-6-deficient (IL-6−/−) mice." (PMID 26035386, 2015). "Patients with NASH (versus simple steatosis alone) show significantly increased expression of IL-1β and TNFα, while increased IL-6 expression is seen in patients with portal fibrosis (versus lobular fibrosis)." (PMID 24830559, 2014). "IL-6 level was correlated with the degree of steatosis until the patients met the criteria of NASH when their blood IL-6 levels decreased." (PMID 24252302, 2013). "Treatment of mice with IL-6 ameliorated steatosis in different models of fatty liver, including ob/ob mice and ethanol-fed mice." (PMID 24066058, 2013). "Multiple chemokines and cytokines have been implicated in the development of steatosis and the progression to NASH; including IL-6, TNF-α, MCP-1 and IL-10." (PMID 24039859, 2013). "More recently, treatment of mice with IL-6 ameliorated steatosis in different models of fatty liver, including ob/ob mice and ethanol-fed mice." (PMID 19936233, 2009). "In parallel, sympathetic input enhances the pro-inflammatory state by promoting Kupffer cell cytokine production, particularly tumor necrosis factor-alpha (TNF-α) and interleukin-6 (IL-6), thereby pushing the progression from steatosis to steatohepatitis 173,174." (PMID 41424854, 2026). "In hepatocytes, IL-6 can also remodel lipid flux: experimental IL-6 administration reduces steatosis by increasing mitochondrial fatty acid oxidation and enhancing VLDL export, indicating an upstream influence on hepatic NEFA handling during high lipid load states." (PMID 41373870, 2025). "Likewise, MO (particularly at 1.0%) effectively restrained HCD-induced steatosis, hepatic interleukin (IL)-6 production, and protected the kidneys, testes, and ovaries from oxidative stress and cellular senescence." (PMID 41011207, 2025). "Therefore, the upregulation of Il-6, Tnf, Mapk13, and Col1a1 pathways under KD at TN likely drives steatosis progression to MASH and fibrosis." (PMID 40864559, 2025). "While chronic IL-6 may promote steatosis/fibrosis in other contexts, in acute metabolic stress it supports hepatocyte homeostasis and regeneration—consistent with a time- and dose-dependent, “double-edged” hepatic role." (PMID 41373870, 2025). "Typically, IL-6 has the effects of protecting the liver and regulating liver regeneration; however, high levels of IL-6 disturb liver regeneration, stimulate hepatocytes to produce various pro-inflammatory factors, promote hepatocyte steatosis, and exacerbate sinusoidal endothelial cell injury." (PMID 41169390, 2025).
steatosis (continued). "Additionally, IL-17 disrupts insulin signaling to worsen steatosis and synergizes with FFAs to induce IL-6 production in both HepG2 cells and murine hepatocytes." (PMID 41394841, 2025). "Interestingly, blocking IL-6 signaling with anti-IL-6Rα enhanced steatosis but reduced inflammation, thereby supporting the role of IL-6 trans-signaling in inflammation." (PMID 38664334, 2024). "However, nothing is known about the degree and clinical relevance of hepatic IL-6 expression in human NAFLD, or about the possible pathways that connect steatosis to elevated IL-6 production." (PMID 38535313, 2024). "Our results are in line with this triculture study in which both their and our activating mixture increased steatosis in hepatocytes, elevated inflammatory cytokines and chemokines including IL-6, IL-8 and MCP-1, and increased fibrogenic activation markers such as collagen in hepatic stellate cells." (PMID 37927606, 2023). "For this, we evaluated whether the increased IL-1β levels were responsible for the exacerbated damage induced by the inhibition of either IL-6 or IL-10 action in liver grafts from DBDs, in the absence and presence of steatosis, respectively." (PMID 37593740, 2023). "The rise in the circulatory inflammatory cytokines interleukin-1β, interleukin-6 and tumor necrosis factor-α and increase in hepatic stiffness and steatosis in battery factory workers after chronic exposure to lead were reduced following chelation therapy with intravenous CaNa2EDTA." (PMID 37090774, 2023). "Interleukin 6 and TNFα play a central role in the promotion of liver inflammation and steatosis." (PMID 36232372, 2022). "ADMSCs infusion reduced liver weight, steatosis and expression of IL‐6, TNF‐a, and F4/80." (PMID 34985174, 2022). "Coincident with an alleviation of hepatic steatosis, we computationally detected the downregulation of IL-6/JAK/STAT3 signaling and the inflammatory response (e.g., Tlr8, Mlkl), together with impaired EMT (Lgals1) in the liver, while the expression of genes related to mTOR was enhanced by LY." (PMID 35737463, 2022). "Although no changes in hepatic gluconeogenesis gene expression were observed between WT and Gkn1−/− mice, there were significantly decreased levels of IL1β and IL6 mRNA in Gkn1−/− suggesting that the resistance to steatosis was accompanied by reduced hepatic inflammation in Gkn1−/− mice." (PMID 33947892, 2021). "IL-6 correlated negatively with steatosis grade (r = –0.544, P < 0.01), ballooning (r = –0.432, P < 0.05), acidophil bodies (r = –0.440, P < 0.05), classification of steatohepatitis (r = –0.415, P < 0.05) and fibrosis septa around the central vein (r = –0.580, P < 0.01)." (PMID 34305638, 2021). "Thus, the activated macrophage increases the expression of inflammatory cytokines, such as tumor necrosis factor (TNF-α) and interleukin-6 (IL-6), which contribute to subsequent steatosis and glucose metabolism disorder." (PMID 32134969, 2020). "It was recently reported that IL-6 enhances fatty acid synthesis in murine hepatocytes via the induction of the citrate transporter mIndy and it also exacerbates hepatic inflammation and steatosis." (PMID 32555600, 2020). "Additionally, procyanidins exert a protective effect against ALD ameliorating SREBP-1-mediated steatosis and inflammation via IL-6 or TNF, with a possible involvement in preventing mitochondrial dysfunction and apoptosis." (PMID 33203174, 2020). "Our results instead showed a clear down-regulation of IL6 in both steatosis and NASH patients." (PMID 33324350, 2020). "This hydroxycinnamic compound also fibrosis development mediated by pro-inflammatory citokines such as TNF, IL-6 and IL-1β and scavenges ROS production in alcohol consumption, reducing the steatosis, apoptosis and fibrosis development pathways mediated by TNF and TGF-β." (PMID 33203174, 2020).